TFAP2C (transcription factor AP-2 gamma)
Diseases named in the same sentence as TFAP2C in open-access papers (continued):
Sharing a sentence is not in itself a finding about the gene and the disease.
cancer (37 papers, 2008 to 2025). A tumor composed of atypical neoplastic, often pleomorphic cells that invade other tissues. "Aberrant expression of transcription Factor AP-2 Gamma (TFAP2C) has been reported to be implicated in malignant process of many cancers." (PMID 29439714, 2018). "Since Tfap2c deficient primordial germ cell-like cells display cancer related deregulations in epigenetic remodeling, cell cycle and pluripotency control, the Tfap2c-knockout allele was bred onto 129S2/Sv genetic background." (PMID 23967156, 2013). "Similarly, altered TFAP2C was also significantly enriched in ER-negative cases, but was additionally associated with luminal B as well as claudin-low cancers." (PMID 40790295, 2025). "TFAP2C signaling is implicated in malignant progression of many cancers." (PMID 33269540, 2021). "To further confirm that TFAP2C drives cisplatin resistance and cancer stemness by binding to the YAP promoter, we added experiments with exogenous overexpressing TFAP2C to explore its effect on cisplatin sensitivity and cellular phenotype." (PMID 40541807, 2025). "Slug binds to miR-137 promoter E-box and upregulates its expression, which promotes cancer invasion and progression through transcription factor AP-2 gamma (TFAP2C) suppression." (PMID 40332376, 2025). "Next, the sphere formation Assay showed that overexpressing TFAP2C significantly increased sphere formation, indicating an increase in stemness of cancer cells." (PMID 40541807, 2025). "Mechanically, TFAP2C positively regulates CTNNB1 transcription via binding to the CTNNB1 promoter in cancer cells." (PMID 40837414, 2025). "TFAP2A and TFAP2C are two members of the AP-2 family of TFs that play important roles in cancer development, but also in early embryonic development, especially of the neural crest and trophectoderm, where they have both redundant and non-redundant functions." (PMID 39853537, 2025). "Similar to TFAP2A, the TFAP2C gene was mainly overexpressed among various cancers and this observation is true for both LUAD and LUSC subtypes (p < 0.001)." (PMID 36831334, 2023). "Taken together, these studies demonstrate a potential mechanism of TFAP2C-mediated overexpression of NANOS3 in cancer." (PMID 36012673, 2022). "Transcription factor AP-2 gamma (TFAP2C) is involved in cancer development and chemotherapy sensitivity." (PMID 36230734, 2022). "Results based on TCGA (The Cancer Genome Atlas), GTEx (The Genotype-Tissue Expression) and GEO (Gene Expression Omnibus) data showed that TFAP2C expression was upregulated in BCa tissues and that its high expression was associated with poor prognosis." (PMID 36230734, 2022). "In recent years, many studies have shown that transcription factor AP-2 gamma (TFAP2C) acts as a key player in cancer development and and its expression level is closely related to the sensitivity of tumors to cisplatin." (PMID 36230734, 2022). "AP-2γ, coding by gene TFAP2C, is highly expressed in cancer tissues and was involved in cancer progression." (PMID 36476988, 2022). "Although these previous studies have indicated the importance of TFAP2C in cancer progression, its roles in NSCLC remain to be investigated." (PMID 31296259, 2019). "Recently, it was reported that TFAP2C participates in the enhancement of cancer stemness and chemoresistance in colorectal cancer." (PMID 31296259, 2019). "Cancer invasion and progression are promoted through TFAP2C suppression." (PMID 40332376, 2025). "Upregulated TFAP2A and TFAP2C tend to be observed more frequently in “stem-like” cancers." (PMID 37291585, 2023). "Similarly to NANOS3 overexpression in cancer, TFAP2C overexpression was also reported in various cancer types." (PMID 36012673, 2022).
cancer (continued). "TFAP2C is upregulated in various cancer types and plays a role in tumorigenesis." (PMID 36028903, 2022). "Methods that suppress TFAP2C promote cancer cell migration and invasion." (PMID 29615098, 2018). "However, it is important to point out that both TFAP2A and TFAP2C have been reported to have dual roles in carcinogenesis, i.e. either inhibitory or promoting depending on the specific tissues and stages of cancer progression." (PMID 24023917, 2013). "Bicluster 1 CpGs were found enriched in binding regions of TFs including GRHL2, TFAP2C, FOXA1, ER, CEBPB and NR5A2, TFs known to be important in many cancer‐related functions such as proliferation, stemness and epithelial‐to‐mesenchymal transition (EMT)." (PMID 38671580, 2024). "We also note that transcription factor motif enrichment analysis of the cancer-specific enhancers revealed FOXA1, MESP1/2, and TFAP2C as the top three transcription factors enriched at these enhancers based on adjusted p-value." (PMID 37685859, 2023). "Numerous scientific reports describe differential expression of these TF and their genes in various types of cancer, identifying among them a potential oncogene or suppressor like TFAP2A or TFAP2C." (PMID 36831334, 2023). "Transcription factor AP-2 gamma(TFAP2C) is a transcription factors shaping ferroptosis sensitivity, which provided novel insights into cancer therapy." (PMID 35719954, 2022). "The DSV (g.4260 T > C) may create a binding site for zinc finger transcriptional repressor hypermethylated in cancer 2 (HIC2) and modify binding sites for TFAP2B and TFAP2C." (PMID 31775637, 2019). "Furthermore, CTNNB1 knockdown did not affect the TFAP2C expression at the mRNA or protein level in these cancer cells." (PMID 40837414, 2025). "The observed overexpression in most cancer types, including LUAD and LUSC, may suggest rather oncogenic potential of these gene family members, and this finding is most highlighted in the case of TFAP2A and TFAP2C genes through both TIMER and GEPIA databases." (PMID 36831334, 2023).
TFAP2C also shares sentences with these, for which no sentence is quoted: ovarian carcinoma (2 papers); acute myeloid leukemia (1); adenocarcinoma (1); autism (1); cervical cancer (1); choriocarcinoma (1); endometrial cancer (1); fragile X syndrome (1); germinoma (1); glioblastoma (1); Hypertension (1); invasive carcinoma (1); liver failure (1); mastitis (1); medulloblastoma (1); metastatic melanoma (1); nasopharyngeal carcinoma (1); pituitary adenoma (1); squamous cell lung carcinoma (1); testicular tumors (1); thyroid cancer (1); type 2 diabetes mellitus (1).